ENSG00000252016
Synonyms: LOC124900505
Gene: Small nucleolar RNA gene on chromosome X (88,148,792 to 88,148,918, forward strand). Ensembl gene ENSG00000252016.
Gene Ontology:
Biological process: RNA processing
Cellular component: nucleolus
Homologues: Orthologues: mouse Gm22156 (65% identical), rat LOC120096840 (61% identical). Paralogues in human: SNORA78 (72% identical).